AR (androgen receptor)
Diseases named in the same sentence as AR in open-access papers (continued):
Sharing a sentence is not in itself a finding about the gene and the disease.
breast carcinoma (continued). "The interaction between AR and GATA3 we discovered herein in breast cancer may in part explain why AR has distinct roles in breast compared to prostate tissues." (PMID 38317241, 2024). "The peptide was produced to inhibit AR transactivation in breast cancer cell lines." (PMID 37903548, 2024). "AR has distinct roles in different subtypes of breast cancers." (PMID 38339092, 2024). "Moreover, the inhibition of AR by antiandrogens such as enzalutamide or by shRNA reduced the cell growth of HER2-positive breast cancer cell lines." (PMID 38339092, 2024). "Furthermore, individual patient data was plotted via open web-based tools to generate average ME scores, CTS5 scores, Predict Breast cancer 10-year survival rate and correlation was drawn with AR expression." (PMID 39650747, 2024). "The expression of AR is noted in a significant proportion of breast carcinoma cases." (PMID 39497884, 2024). "Breast cancer patients who are ER positive are more likely to be AR positive." (PMID 38877071, 2024). "For instance, it has been observed that the estrogen receptor (ER) inhibits the expression of the miR-221/222 genes in breast cancer, while in the progression of PCa, miR-125b, miR-21, and miR-221/222 could be directly regulated by the androgen receptor (AR)." (PMID 39796656, 2024). "Salivary duct carcinomas (SDC) can present with distinct immunologic profiles similar to breast cancer, such as androgen receptor (AR) and HER-2/Neu-positivity, raising the hypothesis that these tumors may respond to hormonal signaling." (PMID 38539538, 2024). "However, the positive expression rate of AR in salivary duct carcinoma can reach 56–97.8% and in breast cancer can reach 60–90%." (PMID 38263473, 2024). "Therefore, in the context of ER+ breast cancer, the interaction between AR and GATA3 likely plays a role in reprogramming ER signaling to inhibit proliferation and promote terminal differentiation." (PMID 38317241, 2024). "In breast cancer cells, AR may have roles in either cell proliferation (stimulatory effect) or antiproliferation (inhibitory effect), depending on the level of ERα expression and disease stages." (PMID 38339092, 2024). "However, a closer assessment of the AR/ER protein ratios in ER+ breast cancer is crucial, given its dual effects on tumor cell growth and immunosuppressive effects." (PMID 39684829, 2024). "This study is useful to better understand the role of steroid hormones in TNBC and the importance of studying the expression of different hormone receptors, such as AR and ERβ, in addition to the conventional ones currently used for breast cancer classification." (PMID 38338747, 2024). "Last, we sought to determine whether Stat5-regulation of AR mRNA occurs in other tissue types and evaluated two different AR-positive human breast cancer cell lines T47D and MCF-7." (PMID 38416822, 2024). "Thus, the regulation of immune-related factors via EREs and AREs is diverse, suggesting that ER/AR signaling in breast cancer cells likely exerts a complex control over stromal cells." (PMID 39682229, 2024). "Herein, we performed AR RIME experiments to characterize and compare the AR interactomes in cell line models representing ER+ and ER- breast cancer to identify candidate co-regulators of AR signaling and forge new insight into the role and mechanistic basis of AR signaling in breast carcinogenesis." (PMID 38317241, 2024). "Following our earlier findings, both AR agonists (DHT) and antagonists (Enz) may be potentially beneficial in the treatment of ER + breast cancer, depends on the AR/ER ratio in the BC cells." (PMID 38965614, 2024). "Herein, we further demonstrate that KDM4B is an AR/GATA3 target gene in ER- and ER+ breast cancers, supporting the concept of AR co-operating with ER signaling to promote differentiation in ER+ disease and independently promoting differentiation in ER- disease." (PMID 38317241, 2024).
breast carcinoma (continued). "Recently, [18F]enzalutamide was evaluated in prostate cancer xenografts, demonstrating high specificity and stability as an AR-targeted tracer, suggesting that [18F]enzalutamide could potentially be adapted for imaging androgen receptors in breast cancer." (PMID 39768978, 2024). "Since androgen receptor (AR) expression is less prevalent in TNBC than other breast cancer subtypes and AR regulates multiple molecular pathways affecting tumorigenesis and disease progression, the molecular classification of TNBC according to AR expression has gained interest." (PMID 38473871, 2024). "Additionally, various stromal cells express either ER or AR, contributing to the development of breast cancer." (PMID 39682229, 2024). "The clinical importance of androgen receptor (AR) status in breast cancer is uncertain." (PMID 39497884, 2024). "Previous studies revealed that AR+ breast cancer tissues are less infiltrated with macrophages." (PMID 39682229, 2024). "In addition to these receptors, the androgen receptor (AR) plays a complex role in breast cancer pathophysiology, acting as both a promoter and an inhibitor of tumor cell growth under certain conditions of estrogen stimulation." (PMID 39456566, 2024). "Additionally, the role of androgen receptor signaling pathway in breast cancer prognosis and immune infiltration has been previously reported." (PMID 38813086, 2024). "This study suggests that the inhibition of AR might be an effective treatment for some patients with ERα-positive/AR-positive breast cancer." (PMID 38339092, 2024). "Another hormone-activated transcription factor, the androgen receptor (AR), is more frequently expressed than ER in breast cancer, occurring in up to 95% of ER+ and ~ 20–30% of ER- primary tumors depending on detection method and criteria used to determine AR and ER positivity." (PMID 38317241, 2024). "Depending on the specific subtype of breast cancer, the modulation of AR expression or its transcriptional activity by either stimulation or inhibition may be an effective therapeutic strategy." (PMID 38339092, 2024). "The role of AR in breast cancer is complex and varies among different subtypes." (PMID 39769441, 2024). "In HER2-amplified breast cancer, AR behaves as the oncogenic driver instead of ER." (PMID 38339092, 2024). "Exploring how AR function in CAFs influences breast cancer progression may offer new insights into the role of CAFs in breast cancer." (PMID 39682229, 2024). "Furthermore, there was a positive correlation between ER-α and AR protein levels with HER3 protein levels in the 47 breast cancer cell lines for which protein array data were available." (PMID 38228924, 2024). "Additionally, androgens are produced locally in breast carcinoma tissues by androgen-producing enzymes, and the androgen receptor (AR) is commonly expressed in breast cancer cells." (PMID 39682229, 2024). "Out of the 192 breast carcinoma cases, 139 (72.4%) showed AR-positive expression." (PMID 39497884, 2024). "Tamoxifen, an estrogen receptor antagonist, and bicalutamide, an androgen receptor antagonist, can induce senescence in breast cancer or prostate cancer.1377 Trastuzumab and pertuzumab, which are antibodies targeting HER2, cause senescence in breast cancer." (PMID 38763973, 2024). "This peak was in an almost identical position to that detected in AR ChIP in breast cancer cells." (PMID 39088439, 2024). "Reciprocal pull down of GATA3 was associated with detection of AR in a DHT-dependent manner in the ER- breast cancer cell lines but not the ER+ lines." (PMID 38317241, 2024). "The prognostic value of AR in ERα-positive breast cancer has been demonstrated in many studies." (PMID 38339092, 2024). "The immunohistochemical evaluation of AR status can help in predicting the prognosis as well as may lead to the use of new treatment modalities in breast cancer especially for triple-negative tumors." (PMID 39497884, 2024).
breast carcinoma (continued). "The fact that AR levels exceed 70% in both primary and metastatic breast cancer suggests that AR could be a novel therapeutic target for AR+ breast cancer patients." (PMID 38215156, 2024). "PR has demonstrated repression of AR within both the endometrium and mammary cancer cells." (PMID 39088439, 2024). "Our results demonstrated that HR and AR status was closely related to HER2-low breast cancers." (PMID 37524746, 2023). "Moreover, in ER+ primary breast cancers, AR positivity correlates with lower tumor grade, burden, and Ki67 labeling index, as well as with a better clinical outcome." (PMID 37686282, 2023). "Although the function of AR in breast cancer depends on the tumor subtype, treatment, and other factors, it is suggested to have a tumor-promoting role, thereby attracting attention as a new therapeutic target for breast cancer treatment." (PMID 36721218, 2023). "Furthermore, it has been reported that CTCs from breast cancer patients with bone metastasis exhibit active androgen receptor (AR) signaling pathway." (PMID 38041134, 2023). "AR signaling plays a different biological role in different breast cancer types." (PMID 37345085, 2023). "However, there is a complexity to the significance of AR expression in breast cancer, with studies showing that the prognostic and predictive power is dependent on the molecular subtype of the tumour, and other factors such as EGFR." (PMID 36831687, 2023). "Therefore, further studies exploring the prognostic and predictive role of AR in patients with breast cancer subtypes are warranted." (PMID 37099044, 2023). "COX regression analysis was then used to test whether AR status was an independent predictor for the prognosis of each breast cancer subtype." (PMID 37099044, 2023). "Depending on the hormonal status, breast cancer setting and cell type, AR may exhibit different roles, such as oncogenic or tumor suppressor." (PMID 36677847, 2023). "Moreover, it is widely expressed in osteosarcoma, tissues of the prostate, liver, cardiovascular, breast and other human tissues, among which the expression of AR in breast cancer is the third highest." (PMID 36929229, 2023). "Moreover, we found a negative association between high COMMD3 expression and tubule score, ELF5, c-Kit and AR expression in a large cohort of breast cancer cases." (PMID 37072858, 2023). "It has been shown that the androgen receptor (AR) has a variety of functions in breast cancer." (PMID 37900385, 2023). "90% (n = 9/10) of primary breast cancers were AR+, whereas 70% (n = 7/10) of BrM were AR+." (PMID 37345085, 2023). "As is known to all, AR is highly expressed in breast cancer, even in TNBC29." (PMID 37524746, 2023). "AR expression was highest in HR + /HER2 + breast cancer and lowest in TNBC." (PMID 37099044, 2023). "Overall, since metastatic-endometrial carcinomas and NEEC express AR, this may serve as a potential therapeutic target for these patients based on the historical targeted treatment of male prostate and female breast cancers with anti-androgen/AR agents." (PMID 37725629, 2023). "In our analyses of BrM, AR is most frequently expressed in HER2+ BrM (previously reported to be expressed in 76–87% of primary HER2+ breast cancers), and AR is least frequently expressed in TNBC BrM (previously reported to be expressed in 27–35% of primary TNBC)." (PMID 37345085, 2023). "Furthermore, functional investigations in breast cancer cells revealed an interaction between AR and SRARP." (PMID 37602329, 2023). "It was further indicated that positive AR was a good prognostic factor of HER2+ breast cancer." (PMID 37085500, 2023). "The AR is another relevant steroid receptor expressed in breast cancer." (PMID 36980680, 2023). "Moreover, the ultrasound findings of breast cancer with different expression of AR are also different." (PMID 36929229, 2023).
breast carcinoma (continued). "In addition, a low level of AR was correlated with decreased sensitivity to anti-HER2 therapies, as revealed by a preclinical study focusing on the impact of AR signaling on HER2+ER− breast cancer cells." (PMID 37085500, 2023). "The co-expression profile of ErbB receptors might also be useful in predicting prognosis of AR-positive breast cancer patients." (PMID 37099044, 2023). "AR is emerging as an important factor in the pathogenesis of breast cancer and may be a new marker and a potential therapeutic target among AR-positive breast cancer patients." (PMID 38114991, 2023). "Moreover, treatment with AR inhibitor enzalutamide for HER2+ ER− breast cancer decreases HER2 phosphorylation, and treatment with enzalutamide plus trastuzumab further improves the inhibition of cell growth compared to single drug treatment." (PMID 37237509, 2023). "Furthermore, we have highlighted the potential of PD-L1 as a therapeutic target for treating integrin-mediated AR-positive breast cancer cells." (PMID 37681860, 2023). "The variability in concordance between the AR status of primary breast cancers and matched metastases suggests that re-checking AR status in metastatic sites may be of value when considering the use of an AR-targeted therapy." (PMID 37345085, 2023). "The association between AR and DFS of breast cancer subtypes was further analyzed by Log-rank test." (PMID 37099044, 2023). "The role of AR status in breast cancer is currently being widely explored." (PMID 37099044, 2023). "In addition, the 2019 WHO classification recognized the existence of an ER− subtype, but AR+ mammary carcinoma was categorized as a distinct type of BC." (PMID 37626796, 2023). "AR is expressed in the majority of breast cancer BrM and represents a potential therapeutic target." (PMID 37345085, 2023). "Of the 141 breast cancer patients in our study, 102 (72.34%) were AR + and 39 (27.66%) were AR–." (PMID 36929229, 2023). "Finally, the effect of AR status on the prognosis of different subtypes of breast cancer after neoadjuvant therapy was analyzed." (PMID 37099044, 2023). "Luminal androgen receptor (LAR) subtype TNBC patients defined by our TNBC type are less responsive to NAC compared to other TNBC subtypes, but breast cancer patients with positive androgen receptor (AR) expression have favorable long-term clinical outcomes, including overall survival and recurrence." (PMID 37190123, 2023). "Therefore, conducting context-specific molecular studies that focus on biologically significant and clinically relevant pathways regulated by the AR can provide a better understanding of the contradictory effects of the AR in breast cancer." (PMID 37681860, 2023). "Since four RUNX1 binding sites were identified in the KLF4 promoter in a human leukemia cell model and KLF4 has been determined as an AR gene target in breast cancer cell lines, more experiments are needed to define the principal source of KLF4 gene expression activation." (PMID 36766786, 2023). "However, the prognostic value of AR in HER2+ breast cancer and the relationship between AR and the immune microenvironment are controversial." (PMID 37085500, 2023). "One study demonstrated that androgen dehydroepiandrosterone sulfate (DHEAS) inhibited cell growth in AR-expressed HR-negative breast cancer cell lines, while another showed that iron-regulated transporter-like protein 9 (ZIP9) mediated the androgen-induced apoptosis of TNBC cells." (PMID 37237509, 2023). "AR + could be a sign of a better prognosis in overall breast cancer (p < 0.001), as well as in human epidermal growth factor receptor 2 (HER2) overexpression and Luminal B subtypes (p = 0.001 and 0.025)." (PMID 36929229, 2023). "Furthermore, a similar pattern of AR/BAD binding to the ARE site from the cyclin D1 promoter was observed in T47D breast cancer cells." (PMID 37686282, 2023). "Only 1 of 71 cases of AR + breast cancer showed smooth margin (p < 0.001)." (PMID 36929229, 2023).
breast carcinoma (continued). "Furthermore, according to The Human Protein Atlas, AR expression, at both gene and protein levels, is second-highest in breast cancer, after prostate cancer, among various malignancies." (PMID 36721218, 2023). "The expression of AR was also related to the molecular subtypes of breast cancer." (PMID 36929229, 2023). "In addition, the results showed that AR status (HR: 0.135 (0.028, 0.664), p = 0.014) and tumor size (HR: 1.103 (1.048, 1.162), p < 0.001) were independent prognostic factors for breast cancer by multivariate Cox regression analysis." (PMID 36929229, 2023). "Univariate analysis showed that AR expression was associated with older age (P = 0.022), earlier T stage (P = 0.048), lower histological grade (P = 0.034), ER positivity (P < 0.001), PR positivity (P < 0.001) and HER2 positivity (P < 0.001) in breast cancer." (PMID 37099044, 2023). "Interestingly, across all the breast cancer subtypes, AR was present on both the primary and metastatic breast carcinomas, with some metastatic tumors showing elevated AR levels." (PMID 37835396, 2023). "Although the presence of AR in normal and neoplastic breast tissues was revealed decades ago, only in recent years the role played by androgens/androgen receptor (AR) signaling in breast cancer growth and progression, prognosis, and treatment has gained much interest." (PMID 37686282, 2023). "Therefore, all these results indicate that Oxy modulates AR, acting as an AR agonist, which leads to ER+ breast cancer cell death." (PMID 36677847, 2023). "Currently, AR is being actively investigated as a therapeutic target of HER2+ breast cancer." (PMID 37085500, 2023). "In fact, our group has been working on this and we have already discovered potent steroidal AIs that, in addition to aromatase inhibition and/or modulation of aromatase levels, also exhibit ERα- and AR-dependent effects and modulate their expression to induce breast cancer cell death." (PMID 36677847, 2023). "It is suggested that the age, menstrual status, AR expression and whether chemotherapy of breast cancer patients are related to the expression level of vitamin B5." (PMID 36759846, 2023). "Approximately 70–85% of breast cancers express androgen receptor (AR)." (PMID 37099044, 2023). "Thus, by acting as an AI that also modulates ERα, ERβ and AR, Oxy impaired cancer cell growth by disrupting cell cycle and DNA synthesis, and induced apoptosis of sensitive ER+ breast cancer cells." (PMID 36677847, 2023). "The role of AR in breast carcinomas has attracted much attention recently." (PMID 37237509, 2023). "Overall, our study shows that AR is a frequently expressed and promising intracranial molecular target, supporting the investigation of androgen-targeted therapies in the treatment of patients with breast cancer BrM." (PMID 37345085, 2023). "The androgen receptor (AR) is present in up to 95% of HR+ breast cancer patients and is hypothesized to have tumor suppressor qualities in patients with HR+ mBC." (PMID 36980743, 2023). "In addition, a phase II clinical trial in AR-positive/ER-negative advanced breast cancer patients with the AR antagonist bicalutamide demonstrated a clinical benefit rate of 19% at six months with an improved progression free survival of 12 weeks." (PMID 37583424, 2023). "The ultrasound characteristics of AR + and AR– breast cancer were significantly different." (PMID 36929229, 2023). "Androgen receptor is frequently expressed in breast cancer and might be a predictive or prognostic factor and a drug target." (PMID 37085500, 2023). "Since the mode of signaling is very similar for the AR and ER, this could be applicable to both AR- and ER-targeted therapies, which are relevant in prostate and breast cancers, respectively." (PMID 36891053, 2023). "This study shows that AR is expressed in the majority of breast cancer BrM, and may be a useful target for treating breast cancer patients who have BrM." (PMID 37345085, 2023).